AK2 (adenylate kinase 2)
Diseases named in the same sentence as AK2 in open-access papers (continued):
Sharing a sentence is not in itself a finding about the gene and the disease.
lung carcinoma (continued). "Although the earlier works demonstrated a biochemical difference of AK2 in lung cancer cases, the molecular events involved in regulating tumor growth and metastasis remained unknown." (PMID 31780678, 2019). "Our data have probably provided preclinical proof that systematic inhibition of AK2 and autophagy could be therapeutically effective on lung cancer." (PMID 31780678, 2019). "Consequently, targeting AK2 in a subset of lung cancers would be an optimal therapeutic strategy, and AK2 may be a biomarker for predicting responsiveness to lung cancer metastasis treatment." (PMID 34630090, 2021). "Additionally, genes coexpressed with GNG5, such as AK2, are highly expressed in lung cancer and can lead to poor prognosis in patients; besides, RER1 as a coexpressed gene with GNG5, could promote the progression of pancreatic cancer and reduce the survival rate of patients." (PMID 34098960, 2021). "Based on the role of AK2 in the EMT process and in the progression of NSCLC, we next examined the expression levels of EMT markers in lung cancer cells." (PMID 34630090, 2021).
combined immunodeficiencies (5 papers, 2009 to 2022). "In addition to original role of AK2, recent studies revealed that AK2 is a multi-functional protein; human AK2 deficiency is responsible for reticular dysgenesis, the most severe form of inborn human severe combined immunodeficiencies (SCID)." (PMID 35585049, 2022).
immune deficiency (5 papers, 2014 to 2026). "It has been demonstrated that AK2 is mutated in individuals with reticular dysgenesis, a severe form of immune deficiency in humans." (PMID 41012626, 2025). "Given that AK2 deficiency causes neutrophil and T cell deficiency, resulting in severe combined immunodeficiency (reticular dysgenesis), we focused on the role of AK2 in neutrophil differentiation." (PMID 36555730, 2022). "In this study, an AK2 deficiency identified in a five-year old Amish male with a history of immunodeficiency is described as well as the cellular pathophysiology induced by this defect." (PMID 31673062, 2019). "While nine adenylate kinase isoforms have been identified in various tissues, AK2 is the only isoenzyme identified in bone marrow white blood cells pregenitors, leading to the immune deficiency in AK2 deficient patients." (PMID 31673062, 2019). "This reported case illustrates the importance of considering RD caused by AK2 gene mutations in patients with immune deficiency and less severe phenotypes than “classical” RD." (PMID 31673062, 2019). "The results confirm the pathogenicity of the AK2 mutation and demonstrate that reticular dysgenesis should be considered in Amish individuals presenting with immune deficiency." (PMID 31673062, 2019). "In summary, AK2 joins RAG1, ADA as well as ITCH and RMRP genes in the list of known causes of immune deficiency in the Amish population." (PMID 31673062, 2019). "Adenylate kinase 2 (AK2) mutations have been associated with sensorineural deafness and reticular dysgenesis, a severe combined immune deficiency (SCID) with near absence of bone marrow lymphoid and myeloid elements." (PMID 25309931, 2014).
liver cancer (4 papers, 2022 to 2025). An epithelial or non-epithelial malignant neoplasm that arises from the liver. "In liver cancer, it induces autophagy, while in CRC, the histone deacetylase inhibitor trichostatin A (TSA) reduces JAK2/STAT3 signaling, causing AK2/STAT3, leading to damage in 16HBE cells and contributing to asthma development." (PMID 40165005, 2025). "To corroborate that the low levels of AK2 expression in liver tumors affect tumor development in vivo, we examined the effects of AK2 ablation on tumorigenesis in an established mouse model of liver cancer." (PMID 35585049, 2022). "Adenylate kinase AK2 is a key enzyme that catalyses the production of ADP from ATP or AMP, and the TCGA database shows that AK2 is highly abundant in liver cancer." (PMID 40984037, 2025). "To further investigate the clinical relevance of AK2-mediated phosphorylation of LOXL3 and DHODH proteins in liver cancer, we first mined the TCGA-LIHC cohort and showed LOXL3 mRNA was upregulated in tumor tissues." (PMID 37253718, 2023). "Thus, there was an inverse correlation between AK2 and p-ERK levels in human liver cancer tissue samples." (PMID 35585049, 2022).
agranulocytosis (3 papers, 2018 to 2025). "Agranulocytosis is a hallmark of human RD, which already manifests itself in clonogenic precursor cells as AK2‐knockdown progenitor cells have poor proliferative and survival capacities and are blocked in their differentiation towards granulocyte lineages." (PMID 40654267, 2025). "The disease is clinically characterized by congenital lymphopenia, lymphoid and thymic hypoplasia with agranulocytosis and sensorineural deafness and is caused by mutations in adenylate kinase 2 (ak2) gene." (PMID 30233640, 2018). "Mutations in the gene encoding adenylate kinase 2 (AK2) are responsible for reticular dysgenesis (RD), clinically defined by the combination of T– B– NK– SCID, agranulocytosis, and sensorineural deafness." (PMID 31440487, 2019).
deafness (3 papers, 2014 to 2015). An inherited or acquired condition characterized by the complete loss of the ability to hear from one or both ears. "This hypothesis is supported by our present data, especially by our transcriptome analysis as inherited deafness genes (such as COCH (coding for cochlin), TIMM8B, PRPS1 and tRNA synthetase) are downregulated in AK2-deficient cells." (PMID 26270350, 2015).
neutropenia (3 papers, 2014 to 2022). A decrease in the number of neutrophils found in the blood. "For instance, based on the findings in the ak2-deficient zebrafish model, it was suggested that antioxidants may have a therapeutic effect in AK2-deficient neutropenia patients." (PMID 34854832, 2022). "According to these findings and previous reports, we examined whether AK2 deficiency disturbs neutrophil differentiation leading to neutropenia." (PMID 24587121, 2014).
acute myeloid leukemia (2 papers, 2024). Acute myeloid leukemia (AML) is a group of neoplasms arising from precursor cells committed to the myeloid cell-line differentiation. "In addition, a recent study reported that ZDHHC21 is highly expressed in acute myeloid leukemia cells and mediates AK2 palmitoylation as well as mitochondrial localization to promote cancer development." (PMID 38195819, 2024). "Moreover, a recent study reported that ZDHHC21 could regulate oxidative phosphorylation by mediating adenylate kinase 2 (AK2) S-palmitoylation and induce differentiation block and stemness in acute myeloid leukemia." (PMID 38195819, 2024).
asthma (2 papers, 2023 to 2025). "Abnormal immune system response is one of the main factors causing asthma, so if AK2 mutations lead to immune system dysfunction, then this may increase the risk of asthma in patients." (PMID 38013370, 2023). "If mutations in AK2 lead to abnormal growth and differentiation of airway epithelial cells, then this may trigger an inflammatory response in the airways, thereby increasing the risk of asthma." (PMID 38013370, 2023).
breast tumor (2 papers, 2022). "On the one hand, it has been shown that AK2 is a repressor protein of growth for breast tumor cell lines." (PMID 35712500, 2022).
Hyperglycemia (2 papers, 2011 to 2020). An increased concentration of glucose in the blood. "OLAN’s downregulation of the two important glycolytic enzymes ENO3 and AK2 were predicted to increase hyperglycemia." (PMID 33302598, 2020). "The cardiogenic growth factor TGF-β promoted AK1 expression, while knockdown of AK1, AK2 and AK5 activities with siRNA or suppression by hyperglycemia disrupted cardiogenesis compromising mitochondrial and myofibrillar network formation and contractile performance." (PMID 21556322, 2011).
pancreatic cancer (2 papers, 2021 to 2024). "The expression of AK2 was significantly higher in pancreatic cancer tissues compared to para-carcinoma tissues (p < 0.05)." (PMID 39867576, 2024).
pancreatic endocrine tumors (2 papers, 2021 to 2024). "A study discovered that the expression of AK2 is upregulated in metastatic pancreatic endocrine tumors, leading to tumor formation." (PMID 39867576, 2024).
primary immunodeficiency (2 papers, 2014 to 2019). "Hereby we summarize dysfunction of three mitochondrial components described in the context of primary immunodeficiency not traditionally classified as primary mitochondrial disorders: adenylate kinase 2 (AK2), RNA component of mitochondrial RNA processing, endoribonuclease (RMRP), and TAZ genes." (PMID 25309931, 2014).
sensorineural deafness (2 papers, 2019). "The phenotypes observed in our models of ak2 deficiency could explain the mechanism that leads to the sensorineural deafness of RD patients." (PMID 31727854, 2019).
anaemia (1 paper, 2025). "In contrast to the human pathophysiology, Ak2 deficiency is lethal in mice due to severe anaemia, and murine myelopoiesis is less affected." (PMID 40654267, 2025). "In contrast to humans, haematopoiesis‐specific Ak2‐knockout mice exhibit embryonic lethality between E13 and E15 due to severe anaemia caused by an early block in definitive erythropoiesis." (PMID 40654267, 2025).
bladder tumors (1 paper, 2016). "AK3 was not previously connected to CLL or any cancer, apart from the finding that deletion of chromosome 9p frequently occurs in bladder tumors, with chromosome 9 carrying AK1, AK2 and AK3." (PMID 27078856, 2016).
breast fibrosis (1 paper, 2019). Breast fibrocystic change characterized by the prominence of fibrotic changes in the parenchyma. "This study describes a new role of AK2 as potential lymphocyte biomarker of radiation toxicity in patients with grade ≥ 2 radiation-induced breast fibrosis." (PMID 31399108, 2019).
cardiac hypertrophy (1 paper, 2020). "During cardiometabolic stress, mitochondrial AK2 activity is increased in response to increased energy demand and the necessity to maintain the cellular adenine nucleotide pool; moreover higher AK2 is often associated with cardiac hypertrophy." (PMID 33042024, 2020).
ciliary dyskinesia (1 paper, 2009). "Recent studies indicate that derangements in adenylate kinase-mediated energetic signaling due to mutations in AK1, AK2 or AK7 isoforms are associated with hemolytic anemia, reticular dysgenesis and ciliary dyskinesia." (PMID 19468337, 2009).
diabetes (1 paper, 2022). "We therefore set out to further delineate the molecular mechanism whereby Ak2 signaling in the RPE helps maintain retinal vascular homeostasis in diabetes." (PMID 36229454, 2022).
Dyskinesia (1 paper, 2020). A movement disorder which consists of effects including diminished voluntary movements and the presence of involuntary movements. "The elements that link the AK1 and AK2 isoforms and amantadine are dyskinesia and inflammation." (PMID 35300368, 2020). "It has long been known, on the one hand, the positive role or amantadine in managing dyskinesia from PD and, on the other hand, the AK1 and AK2 dysregulation in PD." (PMID 35300368, 2020).
eosinophilia (1 paper, 2016). "Defects in AK2 were not included here as the only OS due to AK2 defect did not comment on eosinophilia." (PMID 27222657, 2016).
glioma (1 paper, 2020). A benign or malignant brain and spinal cord tumor that arises from glial cells (astrocytes, oligodendrocytes, ependymal cells). "Here, AK2, CYB5A and GOLT1B were significantly higher in all glioma sample groups, relative to controls." (PMID 32635403, 2020).
heart failure (1 paper, 2022). Inability of the heart to pump blood at an adequate rate to meet tissue metabolic requirements. "And in adult mice, organ-specific ablation of AK2 can lead to heart failure, which may be related to metabolic dysfunction involved in Krebs cycle and glycolytic metabolite buildup." (PMID 36401332, 2022).
ischemia (1 paper, 2015). A hypoperfusion of the BLOOD through an organ or tissue caused by a PATHOLOGIC CONSTRICTION or obstruction of its BLOOD VESSELS, or an absence of BLOOD CIRCULATION. "HA14–1 treatment also induced the AK2 release from mitochondria to supernatant in ischemia-damaged mitochondria." (PMID 25756500, 2015).
leukemia (1 paper, 2024). A malignant (clonal) hematologic disorder, involving hematopoietic stem cells and characterized by the presence of primitive or atypical myeloid or lymphoid cells in the bone marrow and the blood. "zDHHC21 specifically catalyzes the S-palmitoylation of mitochondrial adenylate kinase 2 (AK2) and activates OXPHOS in these leukemia cells." (PMID 38415253, 2024).
leukopenia (1 paper, 2025). "AK2‐deficient patients show a generalized leukopenia that affects both the lymphoid and myeloid cell compartments." (PMID 40654267, 2025).
neuroblastoma (1 paper, 2020). Neuroblastoma (NB) is the most common solid, extracranial childhood tumor. "In our previous study on neuroblastoma (NB), which contains numerous CSC, and embryonal carcinoma cells, we also found that those cells have a high activity of AK2." (PMID 32509571, 2020).
non-small cell lung carcinoma (1 paper, 2021). A group of at least three distinct histological types of lung cancer, including non-small cell squamous cell carcinoma, adenocarcinoma, and large cell carcinoma. "However, although the relationship between AK2 and tumors has long been reported, the role and underlying mechanisms of AK2 in tumors, especially in non-small cell lung cancer, is still unclear." (PMID 34630090, 2021). "To further confirm the expression levels of AK2 in non-small cell lung carcinoma, we downloaded and analyzed existing clinical data from The Cancer Genome Atlas (TCGA) database." (PMID 34630090, 2021).
Obesity (1 paper, 2026). Accumulation of substantial excess body fat. "We have previously shown that AK2 expression is downregulated also in SAT in severe obesity." (PMID 41077621, 2026). "Thus, the downregulation of AK2 may at least partly explain why adiponectin production is compromised in obesity." (PMID 41077621, 2026). "Proteins involved in energy metabolism, such as AK2, ADH1B, ACADS, and GCDH, were downregulated in patients with obesity, suggesting impaired lipid metabolism and mitochondrial dysfunction." (PMID 41077621, 2026).
oral cancer (1 paper, 2014). "UM1 and UM2 oral cancer cells were transfected with siRNA to transketolase (TKT) or siRNA to adenylate kinase (AK2), and Western blotting was used to confirm the knockdown." (PMID 24666435, 2014). "AK2 was over-expressed in the oral cancer cells, especially in low invasive UM2 cells, when compared to NHOKs." (PMID 24666435, 2014). "In this study, we have demonstrated that the knockdown of TKT or AK2 expression significantly inhibits the proliferation of oral cancer cells." (PMID 24666435, 2014). "While AK2 is a significant component of cellular metabolism and adaption, it has not yet been linked to oral cancer." (PMID 24666435, 2014). "siRNA silencing of TKT or AK2 was performed on UM1 and UM2 oral cancer cells, which were both derived from a same tongue squamous cell carcinoma, and the effects of their inhibition on cell proliferation, cellular uptake of glucose and glutamine and lactate production were investigated." (PMID 24666435, 2014).
Pancytopenia (1 paper, 2016). An abnormal reduction in numbers of all blood cell types (red blood cells, white blood cells, and platelets). "Reticular dysgenesis, due to mutations in adenylate kinase 2 (AK2), results in severe pancytopenia which includes monocytes, dendritic cells, and lymphoid cells." (PMID 27755182, 2016).
schizophrenia (1 paper, 2024). A major psychotic disorder characterized by abnormalities in the perception or expression of reality. "AK2, known to be associated with mitochondrial ATP production, was found to be significantly upregulated in the peripheral blood of schizophrenia patients (p = 0.0313)." (PMID 39543767, 2024). "In our research, we uncovered a novel pathway, ERVWE1/circ_0001810/miR-1197/AK2 that significantly influenced mitochondrial energy and morphology in schizophrenia." (PMID 39543767, 2024). "In the context of schizophrenia, AK2, an adenylate phosphotransferase located in the intermembrane spaces of mitochondria, emerges as an intriguing subject." (PMID 39543767, 2024). "Despite its potential relevance, research into AK2's mechanisms in relation to schizophrenia has been surprisingly limited." (PMID 39543767, 2024). "In this study, we presented clinical data indicating increased levels of circ_0001810 and AK2 in schizophrenia, correlating with ERVWE1." (PMID 39543767, 2024). "The bioinformatics analysis of the schizophrenia datasets revealed increased levels of AK2 and enrichment of mitochondrial dynamics." (PMID 39543767, 2024). "A comparative study of AK2 protein levels in the plasma of 34 schizophrenia patients and 30 healthy controls revealed a significant increase in the patient group (p = 0.0054)." (PMID 39543767, 2024). "The GSE53987 dataset, an RNA microarray dataset from the postmortem striatum of individuals with schizophrenia and healthy controls, revealed elevated AK2 levels, hinting at its potential pathophysiological role." (PMID 39543767, 2024). "We also measured miR-1197 and AK2 levels in the blood of schizophrenia patients and healthy controls, observing a decrease in miR-1197 levels in schizophrenia patients (p = 0.001), with medians levels of 0.011 in schizophrenia patients and 4.195 in controls." (PMID 39543767, 2024). "In our data, we observed that AK2 instigated mitochondrial depolarization, implying that AK2 might be a key player in the pathogenesis of schizophrenia." (PMID 39543767, 2024). "Additionally, we observed a similar upregulation of AK2 in the schizophrenia dataset GSE25673 and GSE12649." (PMID 39543767, 2024). "Circ_0001810 and AK2 were increased in schizophrenia and positively correlated with ERVWE1." (PMID 39543767, 2024). "Our findings proposed that ERVWE1 influenced mitochondrial dysfunction through circ_0001810/miR-1197/AK2, which could play a significant role in the pathology of schizophrenia." (PMID 39543767, 2024). "Notably, miR-1197 was reduced in schizophrenia patients, while AK2 levels were increased." (PMID 39543767, 2024).
Sepsis (1 paper, 2019). Sepsis is defined as life-threatening organ dysfunction caused by a dysregulated host response to infection. "While most patients with AK2 mutations published to date had severe sepsis in the newborn period, this patient had a less severe phenotype including delayed clinical presentation of sepsis and response to G-CSF." (PMID 31673062, 2019).
temporal lobe epilepsy (1 paper, 2024). A localization-related (focal) form of epilepsy characterized by recurrent seizures that arise from foci within the temporal lobe, most commonly from its mesial aspect. "AK2 is a protein whose levels are elevated in the rat hippocampus, playing an essential role in temporal lobe epilepsy (TLE)." (PMID 39543767, 2024).
thyroid cancer (1 paper, 2025). "To validate one of the top seven prognostic gene candidates, we selected AK2 to investigate its potential as a biomarker for stratifying thyroid cancer progression and treatment." (PMID 40861812, 2025). "Furthermore, functional studies reveal that AK2 plays a key role in thyroid cancer progression." (PMID 40861812, 2025).